CA1 (carbonic anhydrase 1)
Description:
Catalyzes the reversible hydration of carbon dioxide. Can hydrate cyanamide to urea.
Synonyms: CAB; CA-I; Car1; HEL-S-11
Tractability: Small molecule: an approved drug acts on it; a structure with a bound ligand is known; a high-quality ligand is known; it has a binding pocket of medium quality; it belongs to a druggable protein family. PROTAC: a small molecule that binds it is known.
Target class: Enzyme; Lyase
Gene: Protein-coding gene on chromosome 8 (85,327,608 to 85,379,014, reverse strand). Ensembl gene ENSG00000133742.
Subcellular location: Cytoplasm
Pathways (Reactome):
Transport of small molecules: Erythrocytes take up carbon dioxide and release oxygen; Erythrocytes take up oxygen and release carbon dioxide
Immune System: Gene and protein expression by JAK-STAT signaling after Interleukin-12 stimulation
Metabolism: Reversible hydration of carbon dioxide
Gene Ontology:
Molecular function: arylesterase activity; carbonate dehydratase activity; cyanamide hydratase activity; hydro-lyase activity; protein binding; zinc ion binding
Biological process: response to fructose
Cellular component: extracellular exosome; cytoplasm; cytosol
Genetic constraint (gnomAD): Loss-of-function variants: 11 observed, 9.44 expected, observed/expected ratio (o/e) 1.17, 90% interval 0.73 to 1.8. That is too few expected variants to judge how well the gene tolerates losing a copy. Missense variants: 141 observed, 141.59 expected, observed/expected ratio (o/e) 1, 90% interval 0.87 to 1.14. Synonymous variants: 53 observed, 51.65 expected, observed/expected ratio (o/e) 1.03, 90% interval 0.82 to 1.29.
Homologues: Orthologues: chimpanzee CA1 (99% identical), macaque CA1 (95% identical), dog CA1 (84% identical), pig CA1 (82% identical), guinea pig CA1 (82% identical), rat Car1 (81% identical), mouse Car1 (78% identical), tropical clawed frog ca1 (61% identical), zebrafish ca2 (61% identical), zebrafish cahz (61% identical), Caenorhabditis elegans cah-5 (34% identical), Drosophila melanogaster CARPB (31% identical), and 12 more. Paralogues in human: CA13 (60% identical), CA2 (60% identical), CA3 (54% identical), CA7 (51% identical), CA5A (49% identical), CA5B (48% identical), CA12 (37% identical), CA8 (36% identical), CA14 (34% identical), CA10 (32% identical), CA6 (31% identical), CA9 (31% identical), and 2 more.
Diseases named in the same sentence as CA1 in open-access papers:
CA1 is named in the same sentence as 123 diseases in open-access papers, as found by Europe PMC text mining. Sharing a sentence is not in itself a finding about the gene and the disease. The quoted sentences say what the papers report.
breast carcinoma (11 papers, 2015 to 2025). "Studies have suggested that the CA1 protein contributes to microcalcification in breast cancer and atherosclerosis, and high levels of blood CA1 are detected in patients with breast cancer." (PMID 36788595, 2023). "Using GAPDH as a reference, western blotting revealed that the expression of CA1 was significantly increased in the breast cancer samples, compared to the breast fibroadenoma samples (p = 0.008)." (PMID 26459317, 2015). "Recently, CA1 gene amplification was detected in approximately 25% of breast cancer studies." (PMID 31861902, 2019). "In the present study, we genotyped Tag SNP rs725605 in cohorts of patients with various types of tumours and found that this tag SNP, which is located in the intron 1 region of the gene that encodes CA1, was strongly associated with breast cancer but with no other tumours." (PMID 26459317, 2015). "Our previous study demonstrated that carbonic anhydrase 1 (CA1) stimulates ossification and calcification in ankylosing spondylitis and breast cancer." (PMID 31354482, 2019). "Our results revealed that inhibiting CA1 expression could increase the expression of AR, suggesting that CA1 could regulate AR expression and might therefore influence the progression of microcalcification and other tumourigenic processes during breast cancer tumourigenesis." (PMID 26459317, 2015).
atherosclerosis (9 papers, 2019 to 2024). A disease characterized by the build-up of fatty material and calcium deposition in the arterial wall resulting in partial or complete occlusion of the arterial lumen. "It has been reported that carbonic anhydrase I (CA1) is a target for the diagnosis and therapy of atherosclerosis (AS) since CA1 can promote AS aortic calcification." (PMID 39081633, 2024). "Increased expression of CA-1 mediated calcification and cytokines has been found in atherosclerosis in a mouse model." (PMID 34945756, 2021). "We previously reported that carbonic anhydrase I (CA1), a CA family member, was highly expressed in atherosclerotic tissues of the aorta and stimulated atherosclerosis (AS) by promoting calcification." (PMID 33888852, 2021).
colorectal cancer (8 papers, 2005 to 2025). A primary or metastatic malignant neoplasm that affects the colon or rectum. "Nonetheless, the downregulation of cytosolic CA I, II and XIII in colorectal cancer may result from reduced levels of a common transcription factor or loss of the closely linked CA1, CA2 and CA13 alleles on chromosome 8." (PMID 29495652, 2018). "The down-regulation of cytosolic CA I, II and XIII in colorectal cancer may result from reduced levels of a common transcription factor or loss of closely linked CA1, CA2 and CA13 alleles on chromosome 8." (PMID 15836783, 2005). "Interestingly, increased expression and staining of CA-1 is found in healthy intestinal mucosa, where it participates in regulation of pH homeostasis and water and ion transport, while decreased CA-1 protein and mRNA levels can be found in benign and malignant colorectal tumors (53, –, 55)." (PMID 30696739, 2019).
diabetes (6 papers, 2014 to 2025). "The potential of human carbonic anhydrase 1 (CA1) as a biomarker for various diseases, including cancers, pancreatitis, diabetes, and Sjogren’s syndrome, has been suggested." (PMID 41228776, 2025).
prostate carcinoma (6 papers, 2005 to 2019). A carcinoma that arises from epithelial cells of the prostate gland. "In a practical application of multiple expression-platform profiling, our analysis of C4-2 and LNCaP prostate cancer cell lines has identified genes such as CA1, CARD14, and EPHA7 that may be involved in prostate cancer progression." (PMID 16042785, 2005). "Although the exact mechanism remains unclear, we believe that CA1 mRNA and/or the enzyme CA I play a crucial role in the malignancy of PC3 prostatic cells and might present a novel strategy for the future treatment of prostatic cancer." (PMID 30916466, 2019).
rheumatoid arthritis (5 papers, 2002 to 2022). A chronic, systemic autoimmune disorder characterized by inflammation in the synovial membranes and articular surfaces. "CA1 (carbonic anhydrase I) is a member of the carbonic anhydrase family that catalyzes the hydration and dehydration of CO2/H2CO3 and gene mutation is associated with rheumatoid arthritis." (PMID 23874591, 2013).
ankylosing spondylitis (4 papers, 2010 to 2023). An autoimmune chronic inflammatory disorder characterized by inflammation in the vertebral joints of the spine and sacroiliac joints. "Carbonic anhydrase I (CA1) is involved in the process of bone formation and is indicated in susceptibility to ankylosing spondylitis and therefore may be important for bone erosion seen in RA." (PMID 37344505, 2023).
malaria (4 papers, 2016 to 2025). Malaria is a serious and sometimes fatal disease caused by a parasite that commonly infects a certain type of mosquito which feeds on humans. "In a study of experimental cerebral malaria (CM) in mice infected with P. berghei, circulating MVs were enriched in proteins with potential roles in malaria pathogenesis, such as carbonic anhydrase 1 (CA-I) and myeloid-related protein 8 (MRP-8)." (PMID 39868784, 2025).
colon carcinoma (3 papers, 2017 to 2023). "Previous studies have shown that CA1 mRNA is significantly reduced in colon carcinoma and that loss of CA1 expression is associated with the disappearance of differentiated epithelial cells." (PMID 36691026, 2023).
COVID-19 (3 papers, 2021 to 2024). A disease caused by infection with severe acute respiratory syndrome coronavirus 2. "Moreover, carbonic anhydrase 1 (CA-1) was found to be a candidate biomarker in platelets, showing a significant increase in COVID-19 patients." (PMID 37681923, 2023). "Furthermore, a significantly increased CA-1 concentration was also found in the plasma of patients severely affected by COVID-19." (PMID 37681923, 2023). "In comparison, clusters D and E had proteins with higher levels in COVID-19 convalescents, e.g. immunoglobulins playing a role in antigen recognition (e.g. IGKV1-27, IGKV1-39, IGHV1-46, IGLV3-1, and PRDX2), hemoglobin subunits (e.g. HBB, HBA1, and HBD), and carbonic anhydrase (CA1)." (PMID 38396092, 2024). "Here, we selected five significant proteins for COVID-19 non-severe versus severe comparison: heparin cofactor 2 (SERPIND1), thyroxine-binding globulin (SERPINA7), angiotensinogen (AGT), carbonic anhydrase-1 (CA1), and carbonic anhydrase-2 (CA2) for docking study." (PMID 33995121, 2021).
depressive episodes (3 papers, 2015 to 2024). "One previous study reported downregulation of plasma CA-1 in patients with BD during depressive episodes; however, another study reported an increase in CA-1 levels in the brains of patients with major depressive disorder." (PMID 34945756, 2021). "Therefore, it was proposed that BDI pathophysiology may be associated with early alterations to lipid metabolism irrespective of the mood state, whereas CA-1 might be involved in the depressive episodes." (PMID 38175142, 2024).
epilepsy (3 papers, 2019 to 2022). A brain disorder characterized by episodes of abnormally increased neuronal discharge resulting in transient episodes of sensory or motor neurological dysfunction, or psychic dysfunction. "Acetazolamide is a CA1 inhibitor that is used in the treatment of epilepsy and as a diuretic, and has been reported to inhibit apoptosis in human brain vascular endothelial cells that had been exposed to Aβ." (PMID 35778717, 2022).
heart failure (3 papers, 2016 to 2021). Inability of the heart to pump blood at an adequate rate to meet tissue metabolic requirements. "Finally, also previously proposed diagnostic markers of heart failure, including carbonic anhydrase 1 (CA1) and ceruloplasmin (CP), were among the more abundant proteins in failing hearts." (PMID 33670142, 2021).
influenza (3 papers, 2021 to 2024). An acute viral infection of the respiratory tract, occurring in isolated cases, in epidemics, or in pandemics; it is caused by serologically different strains of viruses (influenzaviruses) designated A, B, and C, has a 3-day incubation period, and usually lasts for 3 to 10 days. "The antigenic determinant domains (Sa, Sb, Ca1, Ca2, and Cb) were found to be involved in antibody binding, and the major antigenic determinant domains of A/swine/Heilongjiang/GN/2020 were similar to the reference influenza." (PMID 36461007, 2022). "It is noteworthy that most influenza antibodies produced by immunization or infection are directed against five antigen sites on the HA1 globular head, Ca1, Ca2, Cb, Sa, and Sb48–50." (PMID 34966175, 2021). "The ten common DEGs (PCOLCE2, HLA_DPA1, LOC653061, TDRD9, MPO, HLA_DQA1, MAOA, S100P, RAP1GAP, and CA1) that were obtained by overlapping genes from computing the three algorithms [LASSO regression, SVM-RFE algorithms, and RF are candidate key genes for severe influenza." (PMID 38454348, 2024).
Sepsis (3 papers, 2022 to 2026). Sepsis is defined as life-threatening organ dysfunction caused by a dysregulated host response to infection. "CA1 (carbonic anhydrase 1) was found to be up-regulated in sepsis from our results." (PMID 36820206, 2023). "Three proteins, including carbonic anhydrase 1 (CA1) and leucine-rich α -2-glycoprotein (LRG1), were identified in all samples from patients with sepsis compared with those without sepsis." (PMID 35874763, 2022).
adenoma (2 papers, 2011 to 2023). A neoplasm arising from the epithelium. "Moreover, CA1, CHGA, and GCG decreased significantly from normal to adenoma and continued to decrease significantly from adenoma to carcinoma, indicating that these genes continued to play a role in inhibiting the process from normal to adenoma then to carcinoma." (PMID 36944972, 2023).
anaemia (2 papers, 2019 to 2020). "Interestingly, two of the six modules (network modules 1 and 4) contained genes that code for proteins expressed in erythrocytes or other blood components (HBM, RHD, GYPA, GYPC, CA1), or have been implicated in blood-associated diseases like anemia (GYPA)." (PMID 32728112, 2020).
gastric cancer (2 papers, 2016 to 2017). A primary or metastatic malignant neoplasm involving the stomach. "The effects of somatic mutations in genes encoding zinc finger proteins (ZNF721 and ZFYVE16), a purine and pyrimidine metabolism protein (NT5E), carbonic anhydrase(CA1), and cyclic nucleotide phosphodiesterase(PDE10A)on the progress of gastric cancer requires further study." (PMID 27270314, 2016).
Hyperglycemia (2 papers, 2019 to 2020). An increased concentration of glucose in the blood. "In vitro studies confirm that hyperglycemia increases expression of CA-1 in endothelial cells to disrupt vasculogenesis." (PMID 33042024, 2020). "CA1 participates in ischemic-induced cardiac fibroblast development, hyperglycemia-induced endothelial cell death, cell proliferation, proinflammatory cytokine production, and vascular permeability alterations, which can be suppressed by a CA1 inhibitor." (PMID 31781243, 2019).
osteosarcoma (2 papers, 2022 to 2025). A usually aggressive malignant bone-forming mesenchymal neoplasm, predominantly affecting adolescents and young adults. "CA1 is a member of the carbonic anhydrase (CA) family, and an overexpression in osteosarcoma cells leads to calcification with ascorbic acid." (PMID 36551747, 2022).
periodontitis (2 papers, 2024 to 2025). An acute or chronic inflammatory process that affects the tissues that surround and support the teeth. "This includes proteins such as ZG16B and carbonic anhydrase 1, whose relationship with periodontitis remains unclear." (PMID 40384977, 2025). "However, carbonic anhydrase 1 and protein S100-P, they were overexpressed in periodontitis (fold-change around 4.3 for both), as in previous studies; however, their relationship with periodontitis is still unclear." (PMID 40384977, 2025). "In addition, specific biological processes and molecular functions during progressive periodontitis were revealed and a set of hub proteins, including SNCA, CA1, HBB, SLC4A1, and ANK1 was strongly associated with the clinical progression status of periodontitis." (PMID 38802345, 2024). "Herein, SNCA, CA1, HBB, SLC4A1, and ANK1, were identified as hub proteins of periodontitis progression." (PMID 38802345, 2024).
prostatic tumor (2 papers, 2019 to 2020). "In prostatic tumor cells PC3, CA1 mRNA expression increased up to thirteen times during anti-CA I Abs-positive patient’s sera treatment." (PMID 31963697, 2020).
AIDS (1 paper, 2007). A syndrome resulting from the acquired deficiency of cellular immunity caused by the human immunodeficiency virus (HIV). "Since the cA1 peptide was processed for recognition by HIV-1-specific CTLs, we have evaluated the capacity of this peptide to stimulate env-specific T cell memory from AIDS patients." (PMID 18043730, 2007).
aortic aneurysm (1 paper, 2019). A ruptured aneurysm located in the wall of the proximal portion of the descending aorta proceeding from the arch of the aorta. "In the present study, CA1 protein was expressed at high levels in AS tissues of both aortic aneurysm and aortic dissection, with extensive calcification." (PMID 31354482, 2019).
aortic atherosclerosis (1 paper, 2021). A atherosclerosis that involves the aorta. "Recently, we found that CA1 was overexpressed in aortic atherosclerosis tissues." (PMID 33888852, 2021).
aphthous stomatitis (1 paper, 2021). "Additionally, using western blot and ELISA assays, we verified that carbonic anhydrase 1 (CA1) and hemoglobin subunit beta (HBB) proteins are highly expressed during the ulcerative and remission phases of recurrent aphthous stomatitis." (PMID 34341431, 2021).
autism (1 paper, 2022). Persistent deficits in social interaction and communication and interaction as well as a markedly restricted repertoire of activity and interest as well as repetitive patterns of behavior. "The fivefold downregulated MPO, TMCC3, MMP8, CA1, and ELF3 genes and the fivefold upregulated MTRNR2L8 gene can be considered for the early identification of autism patients among Saudis." (PMID 35215271, 2022).
blood disease (1 paper, 2023). A disease that occurs in the blood. "Although CA1 is second only to hemoglobin in content in red blood cells, a deficiency of CA1 does not cause blood disease, possibly because other carbonic anhydrases compensate for its deficiency." (PMID 37175757, 2023).
cardiac hypertrophy (1 paper, 2020). "In the heart, CA-1 is expressed in both endothelial cells and myocardium and upregulation activates the Na+/H+ exchange and calcium influx; when over activated CA-1 causes cardiac hypertrophy." (PMID 33042024, 2020).
diabetic cardiomyopathy (1 paper, 2020). Diabetic cardiomyopathy is a disorder of the heart muscle in people with diabetes. "Moreover, adults with diabetic cardiomyopathy have overexpression of myocardial CA-1, lower capillary density, and worse pathological remodeling after ischemia-reperfusion injury than non-diabetics." (PMID 33042024, 2020).
endometrial cancer (1 paper, 2022). Primary or metastatic malignant neoplasm involving the endometrium (mucous membrane that lines the endometrial cavity). "Quantification analysis in 36 patients with endometrial cancer compared to 36 healthy individuals confirmed the upregulation of APOA1, HBB, CA1, HBD, LPA, SAA4, PF4V1, and APOE." (PMID 36551747, 2022).
Hematuria (1 paper, 2025). The presence of blood in the urine. "We investigated whether carbonic anhydrase 1 (CA1) is a useful marker of hematuria that can serve as an alternative to microscopic erythrocyte quantification in urine." (PMID 40662847, 2025).
lymphedema (1 paper, 2021). Excess fluid collection in tissues, causing swelling. "Considering that hemoglobin may be easily influenced during venipuncture and that the focus of this study was to investigate the oxidative stress associated with lymphedema, we chose four other protein targets (CAT, PRDX2, CA1, and CA2) for further validation of their expression by ELISA." (PMID 33917571, 2021).
macular degeneration (1 paper, 2025). Loss of vision in the central portion of the retina (macula), secondary to retinal degeneration. "Additionally, proteins associated with macular degeneration (CA1, CA2, and HBA1) were uncovered, providing new insights into overlapping mechanisms between DR and other retinal diseases." (PMID 40118382, 2025).
mental disorder (1 paper, 2021). A disease that has its basis in the disruption of mental process. "Although CA-1 has been never associated with any mental disorder because it was reported to mediate cerebral vascular permeability, its patho-mechanism in BD-II still requires further investigation." (PMID 33947873, 2021).
oral squamous cell carcinomas (1 paper, 1983). "Using an indirect immunoperoxidase method, the neoplastic epithelium reacted positively with the Ca1 antibody in only 4 out of 7 oral squamous cell carcinomas and the reaction varied between the specimens as to the intensity and number of positively stained cells." (PMID 6354238, 1983).
prediabetes (1 paper, 2020). "In contrast, carbonic anhydrase 1 (CAH1) and polypeptides from myelin expression factor 2 (MYEF2) 31 and kininogen-1 (KNG1) 32 showed specific abnormalities only in T2D but not in prediabetes." (PMID 32089734, 2020).